IL33 (interleukin 33)
Diseases named in the same sentence as IL33 in open-access papers (continued):
Sharing a sentence is not in itself a finding about the gene and the disease.
infection (continued). "Compared to the non-infected mice, when the infected mice were injected with anti-IL-33 mAb or anti-ST2 mAb, the levels of IgG1 decreased highly significantly in the 1st week post-infection (p < 0.001)." (PMID 38787044, 2024). "cAMP level indeed corroborated with IL-33 production in infection and EPAC and PKA, both the principal downstream effector molecules of cAMP, can facilitate the production of IL-33 in different circumstances." (PMID 38750790, 2024). "Alarmin cytokines, such as IL-25, IL-33, and TSLP, are secreted by various immune and epithelial cells in response to tissue damage, infection, or inflammation." (PMID 38396704, 2024). "IL-12 and IL-23, through innate immune cells and IL-33, by suppressing MDSC, potentiate immune responses during infection and cancer." (PMID 37238964, 2023). "Meanwhile, IL-33 increases the proliferation of CD8+ T cells as well as the production of the type 1 cytokine IFN-γ and TNF-α during infection." (PMID 37153553, 2023). "In this regard, IL-33 regulates the functions of various immune cells through ST2 binding and—following its role as an immune sensor to infection and stress—is involved in the pro-fibrotic remodeling of the myocardium." (PMID 36768322, 2023). "The combination of both TMAO and CFT073 had significant additive effects on the release of IL-18R1 and synergistic effects on the release of IL-6, IL-24, IL-33, LIF, TGF-α, and LAP TGF-β1 compared to CFT073 infection alone." (PMID 37111409, 2023). "On the 14 days post-infection, the effector CD4+ T cells (CD3+CD4+CD44hiCD62Llo) were sorted from lungs and ex vivo stimulated with recombinant IL-25 or IL-33 or the combination of IL-25 and IL-33." (PMID 37337050, 2023). "To further assess a role for IL-33/ST2 signaling in adaptive immunity, we sought to define which leukocyte subsets express ST2 during infection." (PMID 37983247, 2023). "In the present study, to gain better understanding of the role of IL-33 cytokine in immunopathogenesis of HIV/TB coinfection, we aimed to determine whether HIV/TB coinfected patients compared to patients with respective mono infections are associated with alterations in IL-33." (PMID 38035159, 2023). "When Proteobacteria abundance increases in the gut during abdominal infection, IL-33 production is stimulated, IL-33-CXCL16 signaling promotes natural ILC2s accumulation in the lung to protect the lung from infection." (PMID 37304260, 2023). "While total GFAP+ astrocyte numbers were stable, IL-33+ mature-myelinating oligodendrocyte cell numbers (MBP+IL-33+) and overall MBP staining were decreased post-infection." (PMID 37983247, 2023). "Transcriptome profiles of IL-25- and IL-33-treated pulmonary effector CD4+ T cells were analyzed by comparing upregulated genes in Il17rb−/− mice and wild-type mice during infection." (PMID 37337050, 2023). "Mothers with ongoing infection exhibited higher levels of the antiviral mediator IFN-α2, the inflammatory cytokines IL-33 and TNF-α, the antiinflammatory cytokine IL-10, and the chemokine MCP-1." (PMID 37490342, 2023). "To examine this, we infected both WT and Il33–/–mice intracranially with WNV-E218A or ZIKV-Dakar and sacrificed each at 7 days post-infection, removing and processing the brain parenchyma for examination of T cell responses by flow cytometry." (PMID 37983247, 2023). "We went on to isolate human blood ILC2 from multiple healthy donors, expanded them and activated with IL-33, PGD2 and LTE4 for 24 h, prior to infection with dengue virus and examined intracellular dengue envelope protein using flow cytometry after 48 h." (PMID 35869167, 2022). "Additionally, IL-33 may function as an alarmin that alerts the immune system after endothelial or epithelial cell damage during infection, physical stress, or trauma and skin trauma as well as endothelial cell damage have been proposed as crucial events in the development of LoS lesions." (PMID 36362603, 2022).
infection (continued). "Furthermore, we illustrate that IL-33 triggers the excessive generation of medullary thymic epithelial cell (mTEC) IV (thymic tuft cells) in a Pou2f3-dependent manner, as a consequence, disturbs mTEC/cortical TEC (cTEC) compartment and causes thymic involution during severe infection." (PMID 36371464, 2022). "We observed that infected WT mice exhibit a mixed response of Th1 and Th2 already in the initial stage of infection (3dpi), represented by an increase in IFN- γ, IL-1β, IL-33, IL-13 and IL-5." (PMID 34324507, 2021). "For example, NO level is associated with vasoconstriction, pro-inflammatory and cell-mediated immunity (CMI) cytokines, HMGB1, IL-33, neopterin, ICAM1, and complement components are most related to inflammation and infection." (PMID 34679434, 2021). "We therefore infected IL-33−/− and WT BALB/c mice with S. mansoni cercariae and sacrificed them at indicated post-infection time points." (PMID 33482904, 2021). "IL-33, in the presence of IL-25, potentiates ILC2 populations to produce IL-13 to promote intestinal remodeling to facilitate infection resistance with helminths and parasites." (PMID 33431701, 2021). "IL-33 median values were higher in both co-infected groups (HIV and non-HIV) than in the H. capsulatum and P. jirovecii individual infection groups." (PMID 34829225, 2021). "Our previous studies have indicated that primary cultures of alveolar epithelial cells type II from naïve mice had increased expression of epithelial cell-derived cytokines IL-33, TSLP and CCL2 after in vitro infection with RSV." (PMID 33923693, 2021). "At 24 h post-infection, the highest bacterial burdens were found within the air pouches of GAS-infected ST2-KO mice, followed by in GAS-infected IL-33-KO mice, with the lowest burden being found in the GAS-infected WT mice." (PMID 34638904, 2021). "We found that the cell viability of infiltrating cells was significantly decreased in IL-33-KO mice, ST2-KO mice, and WT mice given sST2 proteins post-GAS infection, when compared with that of GAS-infected WT mice at 24 h post-infection." (PMID 34638904, 2021). "To further examine the infiltrating cell numbers within the air pouches, we found that the infiltrating cell numbers were significantly decreased in GAS-infected IL-33-KO, ST2-KO mice and WT mice which were given sST2 proteins at 24 h post-infection." (PMID 34638904, 2021). "On the other hand, murine intradermal infection with the herpes simplex virus (HSV)-2 induced the synthesis of IL-33 by keratinocytes, that in turn activated the synthesis of TNF-α and IL-6 by MCs, key cytokines in reducing the severity of the infection." (PMID 34211473, 2021). "At 4 weeks post-infection, male mice had higher levels of TSLP and IL-33 in the lungs, as well as increased airway mucus visualized by PAS staining and by levels of Muc5ac by quantitative PCR, more lung ILC2, DCs, and OX40L+ cells compared to female mice." (PMID 32397226, 2020). "IL-33 binds to the IL-33 receptor complex, which is composed of ST2 and IL-1 receptor accessory proteins, and has a dual role during infection." (PMID 33178181, 2020). "By augmenting the accumulation and recall of virus‐specific CD8+ memory T cells after infection from vaccinia viruses such as MCMV or LCMV, IL‐33 can promote the production of virus Abs, leading to greater protection against subsequent viral challenge." (PMID 32566227, 2020). "During infection IL-33 and ST2 mRNA increased in parallel in the spleen of wild type (wt) animals and paralleled the immunodetection of ST2+ and IL-33+ cells; their expression was twice as high in BALB/c, compared to B6 mice." (PMID 32571430, 2020). "Neutralization of IL-33 diminished AXPN efficacy and reduced neutrophil infiltration to the site of infection, indicating that IL-33 and neutrophil signaling pathways play a crucial role in this drug’s mechanism of protection." (PMID 32156806, 2020).
infection (continued). "Initial RSV response is driven by innate cytokines, such as IL-25, IL-33, and thymic stromal lymphopoietin (TSLP) that are released from the airway epithelial cells following infection." (PMID 32375305, 2020). "Previous research performed using different helminth models demonstrates a role for MC in the production of IL-25, IL-33, and TSLP, suggesting the possibility of MC priming of these cytokines during early infection." (PMID 30670631, 2019). "Higher expression level of tTG at week 6 in comparison with week 5 and 8 post-infection in both C57BL/6 and Balb/C mice liver led us to evaluate its regulation relationship with IL-33/ST2 at week 6 post-infection." (PMID 31200771, 2019). "Despite pre-infection (day zero), IL-12p40 level in BAL fluids with exogenous IL-33 injection were higher than those with PBS." (PMID 31509992, 2019). "However, the deficiency of endogenous IL-33 did not affect mortality post-infection." (PMID 31509992, 2019). "Infection with influenza virus, rhinovirus, and respiratory syncytial virus (RSV) can all result in ILC2-mediated airway hyperreactivity and inflammation via IL-33 and TSLP production." (PMID 30893756, 2019). "On other post-infection days, higher levels of IL-12p40 were measured in BAL fluids with exogenous IL-33 injection than PBS." (PMID 31509992, 2019). "During infection with lymphocytic choriomeningitis virus (LCMV), splenic IL-33 mRNA levels increase." (PMID 31447845, 2019). "In order to determine if IL-33 mediates protection during infection, we used a mouse model of CDI to ascertain the effect of IL-33 on disease severity, tissue pathology, and mortality." (PMID 31221971, 2019). "It has been shown that IL-33 prevented the downregulation of CXCR2, which is crucial for the recruitment of neutrophils from the circulation to the site of infection, thereby inhibiting their chemotaxis." (PMID 29728738, 2018). "In IL-4-polarized macrophages, a further enhancement of infection was statistically significant for IL-25 alone, TSLP alone, and every combination of IL-33 with the other alarmins." (PMID 30282716, 2018). "Of note, relative levels of MGL1 and IL33 at baseline were higher in BN compared to PVG, and this difference was further amplified following infection." (PMID 30150981, 2018). "When neonatal mice are treated with antibodies to neutralize TSLP, IL-33 or their target expressed on DCs, OX40L, the ability of early RSV infection to prime pathological Th2 responses upon re-infection of adults is reduced." (PMID 29915592, 2018). "Our understanding of the contributions of IL-33 and ST2 during infections is advancing; however, the roles appear to be time, tissue, and model dependent." (PMID 28168040, 2017). "Compared to Mock infection, strain SE2472 infection strongly increased the mRNA levels of inflammatory cytokines including IFN-γ, IL-1β, MIP-2, IL-33, IL-17, IL-22, TNFα, etc.." (PMID 29208934, 2017). "Binding of IL-33 to the IL-33 receptor (IL-33R, or its subunit, known as T1/ST2, or ST2) is a key interaction that initiates responses in allergy and infection." (PMID 28538175, 2017). "Here, we show a decrease of Il33 transcription and an upregulation of IL-33 protein in the hippocampus, the SVZ and the frontal cortex, 7 days post-PbA infection in WT mice." (PMID 28448579, 2017). "Indeed, while IL-33 was originally described as an inducer of type 2 immune responses, its pleiotropic nature is now well documented, including in inducing type 1 responses, and exogenous systemic IL-33 treatment may either protect or exacerbate infections, depending on the infectious disease." (PMID 28448579, 2017). "BALB/c mice were injected with IL-33 or vehicle (phosphate-buffered saline; PBS) on the day of the infection with MCMV and 2 days later." (PMID 28448566, 2017). "Alveolar macrophages are the primary source of increased IL-33 levels during infection, and an in vitro stimulation of these cells with a TLR7 agonist induces IL-33 expression." (PMID 28205524, 2017).
infection (continued). "IL-33 is strongly expressed within the CNS, and we recently showed that the high steady-state levels of IL-33 protein found in naïve brain doubled during ECM, after blood stage or sporozoite PbA-infection." (PMID 28448579, 2017). "At 48 hpi, IL-33 levels were similar to those in controls, but elevation in sST2, ST2L, and Ang2/Ang1 ratio remained significant, especially for high-dose infection groups." (PMID 26943125, 2016). "Both WT and IL-33 KO mice showed a significant inflammatory response to RSV, as measured by total lung cell numbers, compared with those after mock infection (see Fig E5, B)." (PMID 27156176, 2016). "We found an infection dose-dependent increase in the expression of IL-33, ST2L soluble ST2 (sST2), and the Ang2/Ang1 ratio at 24 and 48 hours post-infection." (PMID 26943125, 2016). "Since IL-33 exerts its cytokine activity through a signaling receptor known as ST2L, we examined ST2L expression in liver using mixed and single male infection model." (PMID 27445267, 2016). "IL-33 is expressed primarily in epithelial and endothelial cells, especially in high endothelial venules, and can enhance CD8+ T cell responses to infection, which serve as the first line of defense against microbes in Th2-type immune responses." (PMID 25892854, 2015). "This is further supported by decreased IL-33 expression when CFTRdelF508 AECs are pre-treated with a CFTR corrector (VX-809) and/or potentiator (VX-770) before infection." (PMID 26793709, 2015). "The Th1-specific transcription factor Tbet peaked at day 3 of infection in PBS control mice but was reduced on day 3 and unchanged on day 5 in IL-33-treated mice compared to PBS-treated mice." (PMID 25659095, 2015). "Post albendazole and/or praziquantel treatment, the cellular release of IL-10, IL-33, MIP3-α/CCL20 and MIG/CXCL9 lessened significantly in all children infection groups." (PMID 25698903, 2015). "IL33 expression showed a similarly modest change in expression as IL1A, with levels of mRNA increasing by ∼fourfold at 2 h post-infection." (PMID 24137162, 2013). "We initially observed up-regulated expression of IL-33 and ST2 in chronic hepatitis B and C virus (HBV and HCV) infection in human and in CCl4-induced liver fibrosis in mice." (PMID 24058536, 2013). "The liver sinusoidal endothelial cells and vascular endothelial cells represented inducible expression of IL-33 at 16, 24, 28, 32, 48 and 72h of L2-MHV3 infection compared to vehicle control mice." (PMID 24058536, 2013). "The levels of serum IL-33 and sST2 in 154 patients with CHC, 24 with spontaneously resolved HCV (SR-HCV) infection and 20 healthy controls (HC), were analyzed by ELISA." (PMID 22315510, 2012). "In addition, and similar to IL-1α, increasing evidence indicates that IL-33 can function as a prototypic ‘alarmin’, passively released upon cellular damage, stress, or necrosis, and able to serve as a danger signal/alarmin to alert the immune system of a local threat, such as trauma or infection." (PMID 23062310, 2012). "Together, these findingsdemonstrate that the IL-33/ST2 axis limits early systemic inflammation,orchestrates cardiac immune response, and protects against immunopathologyand electrical remodeling during T. cruzi experimental infection." (PMID 41365681, 2026). "Aside from IL-33, no significant upregulation in other cytokines was detected at early infection stages, as confirmed by the Proteome profiler and ELISA." (PMID 40918106, 2025). "No such reduction in IL-33 or AMs was observed in breakthrough infection mice, which had vaccine protection from sustained viral replication." (PMID 41190814, 2025). "Because IL-33 could activate dendritic cells via the ST2 receptor, we tested activation markers on dendritic cells before (day 0) and at 2, and 5 days of infection." (PMID 40048372, 2025).
infection (continued). "The expectation was that if IL-33 protection from recurrent R20291 infection was due to anti-TcdB2 antibody production, IL-33 would not prevent recurrence from the classical VPI 10463 that produces TcdB1." (PMID 40048372, 2025). "Besides RV and RSV, infection by the influenza A virus triggers the NLRP3 inflammasome, resulting in augmented production of IL-33 by alveolar macrophages." (PMID 40636260, 2025). "When mice, non-infected or infected, were injected with IL-33, the levels of total IgG significantly increased from the 1st week post-infection (p < 0.001)." (PMID 38787044, 2024). "On the contrary, the silencing of PKA did not significantly influence infection-induced IL-33 expression." (PMID 38750790, 2024). "Here, we documented that IL-33 induction is a consequence of elevated cAMP-mediated exchange protein activated by cAMP (EPAC)/calcineurin-dependent signaling and essential for the sustenance of infection." (PMID 38750790, 2024). "IgG3: the levels increased in all IL-33-treated groups with or without infection in the 2nd week post-infection (p < 0.001)." (PMID 38787044, 2024). "It is reported that IL-33 from type II alveolar epithelial cells aids to killing the infected larvae of S. venezuelensis in the lungs by inducing the proliferation of ILC2 and production of IL-5 and IL-13 during the primary infection." (PMID 39559705, 2024). "Cells pretreated with IL-33 antibody did not document any significant change in the rate of infection as well." (PMID 38750790, 2024). "IgG2a, IgG2b, and IgG2c: the levels increased in all infected groups with or without IL-33 in the 1st week post-infection (p < 0.001)." (PMID 38787044, 2024). "Unlike the diffuse production of HMGB1, IL-33 is basically produced in epithelial cells and has a role in tissue inflammation correlated to pathogen infection." (PMID 36675299, 2023). "Interestingly, the intestinal adiponectin expression was strongly associated with the expression of epithelial cell-derived cytokines IL-25, IL-33, and TSLP following infection." (PMID 37635188, 2023). "It should also be considered that the control group included in this study had no history of infection or inflammation, which in turn affects IL-33 levels." (PMID 38035159, 2023). "The release and function of TSLP by dermal TRMs during L. major infection appears to be non-redundant, as neither IL-33 nor IL-25 transcripts were detected in the dermal TRM cluster, and mice deficient in these cytokines did not alter their infection outcome." (PMID 38030609, 2023). "In the absence of IL-33 signaling post-infection, we found defects in microglial activation and survival, leading to enhanced BBB breakdown, increased monocyte extravasation and neuronal apoptosis." (PMID 37983247, 2023). "Unlike that observed in serum, IL-33 levels in the liver are significantly lower in ST2−/− mice compared with WT mice in both stages of infection." (PMID 37373379, 2023). "In order to isolate roles for IL-33 and ST2 within the CNS, we used an established model of intracranial infection with an attenuated form of WNV (WNV-E218A), a model in which most wild-type mice survive infection but display CNS pathology and sequelae." (PMID 37983247, 2023). "IL-33 prevents the TLR signaling-mediated induction of G protein-coupled receptor kinase-2 (GRK2) and maintains the expression of the chemokine receptor CXCR2, allowing neutrophils to migrate to the site of infection for bacterial clearance." (PMID 38082335, 2023). "Previous studies have indicated that infection with C. neoformans stimulated lung epithelial cells to secrete IL-25 and IL-33 but not TSLP19–22." (PMID 37337050, 2023). "IL-33-responsive CD4+ T cells are also a source of type 2 cytokines in the lungs and are important for memory responses to limit Nb-induced lung damage and worm burden during a secondary infection." (PMID 37251384, 2023).